NXPE2 (neurexophilin and PC-esterase domain family member 2)
Synonyms: FAM55B; FLJ25224
Tractability: Antibody: UniProt predicts a signal peptide or a membrane-spanning region.
Gene: Protein-coding gene on chromosome 11 (114,678,527 to 114,707,069, forward strand). Ensembl gene ENSG00000204361.
Subcellular location: Membrane
Gene Ontology:
Molecular function: protein binding
Cellular component: membrane
Genetic constraint (gnomAD): Loss-of-function variants: 13 observed, 18.47 expected, observed/expected ratio (o/e) 0.7, 90% interval 0.46 to 1.12. The upper end of that interval is the gene's LOEUF score, 1.12, which puts it in group 4 of 6, group 1 being the genes least tolerant of losing a copy. Missense variants: 510 observed, 529.3 expected, observed/expected ratio (o/e) 0.96, 90% interval 0.89 to 1.04. Synonymous variants: 185 observed, 189.72 expected, observed/expected ratio (o/e) 0.98, 90% interval 0.86 to 1.1.
Homologues: Orthologues: chimpanzee NXPE2 (98% identical), macaque NXPE2 (95% identical), rabbit NXPE2 (79% identical), guinea pig NXPE2 (75% identical), rat Nxpe2 (70% identical), mouse Nxpe2 (69% identical). Paralogues in human: NXPE1 (68% identical), NXPE4 (61% identical), NXPE3 (29% identical).
Diseases named in the same sentence as NXPE2 in open-access papers:
NXPE2 is named in the same sentence as 6 diseases in open-access papers, as found by Europe PMC text mining. Sharing a sentence is not in itself a finding about the gene and the disease. The quoted sentences say what the papers report.
gastric cancer (1 paper, 2021). A primary or metastatic malignant neoplasm involving the stomach. "NXPE2 (neurexophilin and PC-esterase domain family member 2) could be a predictive signature for diffuse-type gastric cancer heterogeneity." (PMID 33996533, 2021).
NXPE2 also shares sentences with these, for which no sentence is quoted: colitis (1 paper); Crohn disease (1); diabetes (1); inflammatory bowel disease (1); ulcerative colitis (1).